CXCR4 (C-X-C motif chemokine receptor 4)
Diseases named in the same sentence as CXCR4 in open-access papers (continued):
Sharing a sentence is not in itself a finding about the gene and the disease.
colon carcinoma (continued). "Studies on colon cancers and liver cancers have suggested that SDF1 and CXCR4 are involved in cancer lymphatic metastasis and that the mechanism is related to the induction of cell proliferation and directional migration." (PMID 29783989, 2018). "In addition, either in miR-126-overexpressing or in miR-126-silenced colon cancer cells, the restoration of CXCR4 could significantly reverse miR-126-induced suppression of colon cancer cell migration, invasion and proliferation, as well as abolish the effects of miR-126 on RhoA signaling." (PMID 27517626, 2016). "We evaluated the expression and function of CXCR4 and CD26 in colon cancer cell lines and xenografts following treatment with common chemotherapies using radioligand binding, flow cytometry, immunofluorescence, and enzymatic assays." (PMID 26552750, 2015). "Given that CXCL12 can stimulate or repress cell motility in a dose-dependent manner in monocytic leukemia and colon cancer cell lines, we wanted to determine the CXCL12 concentration that is optimal for stimulating CXCR4-mediated motility in LNCaP cells." (PMID 25884570, 2015). "We investigated CXCR4 and CXCR7 mRNA and protein expression in human colon carcinomas and the modulation of their expression by hypoxia and HIF-1α in colon cancer cell lines." (PMID 24629239, 2014). "Our study characterized a large panel of colon carcinoma cell lines and their corresponding xenografts, showing significantly reduced expression of the cell surface markers CD133, CD44, CD24, CDCP1 and CXCR4 in vivo." (PMID 22433494, 2012). "We characterized a panel of fourteen human colon carcinoma cell lines and their corresponding xenografts for the surface expression of potential stem cell markers CD133, CD24, CD44, CDCP1 and CXCR4." (PMID 22433494, 2012). "In order to quantify the message RNA of these marks in colon cancer, expression of HIF-1α, CXCR4, and VEGF at the mRNA levels was analyzed by real-time PCR in different samples." (PMID 20953377, 2010). "In summary, we have demonstrated that HIF-1α, CXCR4, and VEGF are highly expressed in colon cancer samples as demonstrated using immunohistochemistry." (PMID 20953377, 2010). "Results demonstrated that CXCR4, and VEGF expression at the mRNA levels by real-time PCR were similar at the protein levels by immunohistochemistry in colon cancer." (PMID 20953377, 2010). "The results demonstrate that there is a statistically significant correlation between human colon cancer TNM stage and single HIF-1α, CXCR4, and VEGF expression levels." (PMID 20953377, 2010). "We found a correlation of distant metastasis of colon cancer with combined high expression of all three HIF-1α, CXCR4, and VEGF markers." (PMID 20953377, 2010). "Lastly, in order to quantify the message RNA of HIF-1α, CXCR4, and VEGF in colon cancer, the three marks expression at the mRNA levels were analyzed by real-time PCR." (PMID 20953377, 2010). "We further compared correlation of lymph node metastasis of colon cancer with combined high expression of both HIF-1α and CXCR4, of both HIF-1α and VEGF, or of both CXCR4 and VEGF." (PMID 20953377, 2010). "We investigated the clinicopathologic significance of HIF-1, CXCR4, and VEGF expression using immumohistochemistry in human colon cancer." (PMID 20953377, 2010). "The differences in expression of the three molecules (HIF-1α, CXCR4, and VEGF) between benign hyperplastic polyps and colon cancer tissues were all found to be statistically significant (P < .05)." (PMID 20953377, 2010). "The experiment results demonstrated that CXCR4 mRNA and VEGF mRNA expression levels were significantly higher in fresh colon cancer samples than in normal colonic tissue, whereas tumoral HIF-1α expression at the mRNA levels was not higher." (PMID 20953377, 2010). "In this study, we demonstrate high expression of HIF-1α, CXCR4, and VEGF in human colon cancer specimens using immunohistochemistry." (PMID 20953377, 2010).
colon carcinoma (continued). "The mRNA expression of HIF-1, CXCR4, and VEGF werequantified by real-time PCR in different colon cancer tissue samples, the experiment results shown that fresh colon tissue samples significantly overexpressed CXCR4 and VEGF mRNA compared with negative control." (PMID 20953377, 2010). "In addition, we found that miR‐126‐overexpressing colon cancer cells inhibited macrophage recruitment, whereas miR‐126‐silenced cells promoted macrophage recruitment, and the CXCL12/CXCR4 axis mediated the regulatory effects." (PMID 35363937, 2022). "The CXCR-4 and CD133 positivity was found to have prognostic value in colon cancer." (PMID 34885003, 2021). "Overexpression of different mutant versions of CXCR4 lacking signal transduction capabilities also result in marked downregulation of DR5 expression in colon cancer indeed confirms the reverse relationship between DR5 and intracellular CXCR4 protein expression." (PMID 33966046, 2021). "This was carried out using high and low CXCR4-expressing human colon cancer HT29 sublines and SW480 cells with or without lentiviral CXCR4 overexpression." (PMID 35582377, 2021). "We reported, for the first time, that 5-methylcytosine (5mC) distribution in the CXCR4 promoter is not significantly altered in primary colon cancers." (PMID 34298991, 2021). "Several reports connected CXCR4 expression, EMT and metastasis in colon cancer." (PMID 32708431, 2020). "The newly developed CXCR4 antagonist, Peptide R (Pep R), reduced the growth and improved the efficacy of conventional chemo (CT) or chemo-radiotherapy (RT-CT) in a HCT116 human colon cancer model." (PMID 32708431, 2020). "While the inhibition of CXCL12 and CXCR4 can signifcantly reduce tumor cell proliferation and metastasis, indicating that CXCL12 is closely related to development, outcome and prognosis of colon cancers." (PMID 31500630, 2019). "Based on our results, we suggest that the modification of CXCR4, PTEN, or PI3K function might be promising new therapeutic approaches to inhibit the aggressive spread of colon cancer." (PMID 31500630, 2019). "RT-PCR results revealed that all colon cancer cell lines were found to express PTEN and CXCR4 mRNA." (PMID 31500630, 2019). "A study reported that the level of CXCR4 in colon cancer is significantly higher than that in the normal tissues, and increases with the progression of tumor from the early (stages 0–II) to the late stages (III–IV stage)." (PMID 30789971, 2019). "CXCR4 and PTEN were expressed in all colon cancer cell lines." (PMID 31500630, 2019). "Inhibition of microenvironmental CXCL12/CXCR4 signaling may be one approach by which to enhance PTEN phosphorylation, which inhibits colon cancer cell growth." (PMID 31500630, 2019). "While the inhibition of CXCL12 and CXCR4 can significantly reduce tumor cell proliferation and metastasis, indicating that CXCL12 is closely related to development, outcome and prognosis of colon cancers." (PMID 29305742, 2018). "It is reported that PTPRC was predicted to interact with CXCR4, and PTPRC might also play a role in colon cancer metastasis." (PMID 30587197, 2018). "As PTPRC was predicted to interact with CXCR4, we speculated that PTPRC may also be involved in the metastasis of colon cancer to the liver." (PMID 28629469, 2017). "The results indicated that 5-Fu/P85 copolymer micelles could inhibit the growth and metastasis of colon cancer, which could be attributed to the decrease of the content of CD133 + CXCR4+ cells and suppression of EMT of CD133 + CXCR4+ cells." (PMID 26864651, 2016). "It suggests that neither CD133 nor CXCR4 expression allows for identification of cells univocally initiating renewal of HT-29 colon cancer cells after the treatment with 5-FU, both in the absence and in the presence of vitamin D analogues." (PMID 27314328, 2016). "MiR-126 negatively correlated with CXCR4, RhoA, RhoGEF and ROCK in human colon cancer." (PMID 27517626, 2016).
colon carcinoma (continued). "In breast and colon cancer, lower intrinsic levels of the chemoattractant chemokine CXCL12 due to hypermethylation of its promoter disrupt cellular feedback mechanisms to internalize membranous CXCR4." (PMID 27462860, 2016). "In conclusion, PAR1-activated platelets may induce EMT of the SW620 colon cancer cell line via the TGF-β pathway, and they provide chemotactic signals to the SW620 cells which lead to the upregulation of CXCR4 on the cancer cell surface." (PMID 25846512, 2015). "Thus, CXCR4 and CXCR7 seem to play different roles in colon tumors, and further studies are necessary to better understand their respective roles." (PMID 24629239, 2014). "Furthermore, we analyzed the clinicopathologic significance of combined HIF-1α, CXCR4, and VEGF expression in colon cancer." (PMID 20953377, 2010). "Statistical analysis showed that combined high expression of all three molecules (HIF-1α, CXCR4, and VEGF) is significantly associated with lymph node metastasis in patients with colon cancer as compared with cases not showing such expression (P < .001)." (PMID 20953377, 2010). "The mRNA expression of HIF-1α, CXCR4, and VEGF in colon cancer were quantified by real-time PCR." (PMID 20953377, 2010). "By evaluating histological samples from human colon cancer metastases in the liver, we observed that numerous HB-EGF/CXCR4-positive macrophages, which expressed both the M1 CXCL10 and the M2 CD163 markers, indicating a mixed M1/M2 microenvironment, infiltrated metastatic cancer cells." (PMID 20946648, 2010). "To validate our atypical in vitro observation into an in vivo system, we picked three different colon cancer cell lines having different CXCR4 expression patterns, such as HT-29, has robust CXCR4 surface expression and other two DLD-1 and HCT-116 having only intracellular CXCR4 expression." (PMID 33966046, 2021). "The activation of the CXCL12/CXCR4 signaling axis leads to chemotaxis, cell survival, and proliferation, however, the downstream signaling cascades are tissue-specific and not well characterized in colon cancer." (PMID 31500630, 2019). "Furthermore, we investigate whether the expression of HIF-1α, CXCR4, and VEGF have a significant correlation with clinicopathologic factors of colon cancer." (PMID 20953377, 2010). "Moreover, experimental data show that there are statistically significant differences in high expression of single CXCR4 or VEGF molecules, and high expression of both CXCR4 and VEGF molecules with regard to distant metastasis in patients with colon cancer (P = .035 for CXCR4/VEGF)." (PMID 20953377, 2010). "Further investigations providing one explanation for the inhibitory effect of 5-Fu/P85 copolymer micelles on colon cancer, showed that 5-Fu/P85 copolymer micelles could decrease the content of CD133 + CXCR4+ cancer cells in HCT116 and RKO cell lines and suppress EMT of CD133 + CXCR4+ cancer cells." (PMID 26864651, 2016). "However, the lack of CXCR4 expression was found in murine colon carcinoma cells in vitro." (PMID 26592552, 2015). "In SW480 and Colo 205 colon cancer cells, LPS elevated CXCR7 and increased proliferation and migration but not CXCR4." (PMID 34298991, 2021). "Unlike CXCR4, the expression of CXCR7 is not regulated by hypoxia or HIF-1α in colon cancer cell lines." (PMID 34298991, 2021). "We found that CD133+ colon cancer cells isolated from the HCT116 cell line had a greater clonogenic and tumorigenic ability than CD133- cells irrespective of CXCR4 expression." (PMID 22871210, 2012). "Our results demonstrated that the status of CXCR4 expression does not result in different clonogenic and tumorigenic abilities for HCT116 colon cancer cells." (PMID 22871210, 2012). "Statistical analysis shows that the incidence of lymph node metastasis tends to be higher in patients with colon cancer with high rather than low expression of HIF-1α, CXCR4, or VEGF (P < .001, P = .001, P = .001, resp.)." (PMID 20953377, 2010).
hepatocellular carcinoma (118 papers, 2005 to 2025). A malignant tumor that arises from hepatocytes. "Loss of SBP-1 induces increased CXCR4 expression and enhanced invasive and poor prognosis of hepatocellular carcinoma." (PMID 37684566, 2023). "C‐X‐C chemokine receptor type 4 (CXCR4) expression is associated with poor prognosis of hepatocellular carcinoma." (PMID 34555268, 2021). "In hepatocellular carcinoma, CXCR4 and CXCL12 have been associated with variations in the cell cycle resulting in increased risk of metastasis formation in bone, and elevated levels of the chemokine enhances migration of the tumor cells." (PMID 26560447, 2015). "Here, the authors demonstrate that CXRC4 is overexpressed in hepatocellular carcinoma and is associated with poor prognosis and, mechanistically CXCR4 is increased in expression via EZH2 repression of microRNA-622." (PMID 26404566, 2015). "In summary, strong expression of CXCR4 is significantly associated with progressed hepatocellular cancer." (PMID 16819541, 2006). "However, some research has indicated that the EZH2-mediated loss of miR-622 determines CXCR4 activation in hepatocellular carcinoma." (PMID 32635336, 2020). "C‐X‐C chemokine receptor type 4 (CXCR4) expression is associated with poor prognosis of hepatocellular carcinoma (HCC)." (PMID 34555268, 2021). "This study was conducted to analyze the association of CXCR4 expression with hepatocellular carcinoma (HCC) bone metastasis and patient survival." (PMID 19508713, 2009). "Currently, CXCR4 antagonists are approved for cancer treatment, including revamping the antitumor response after immune modulation by hepatocellular carcinoma." (PMID 40581668, 2025). "Our previous studies demonstrated the ability of medium conditioned from these stromal cells to increase aggressiveness of osteosarcoma and hepatocellular carcinoma cells through CXCR4 and AQP1." (PMID 36672233, 2023). "Interstitial flow at 0.7 μm/s and 0.1 μm/s increases cell invasion in glioblastoma and hepatocellular carcinoma through activating CXCR4." (PMID 37864030, 2023). "Other receptors identified recently such as CXCR4 in hepatoma also senses stiffness of ECM and activates YAP/TAZ activation." (PMID 36906534, 2023). "Another study showed that PD-1 blockade combined with CXCR4 inhibition and sorafenib inhibited hepatocellular carcinoma growth." (PMID 36308553, 2023). "Importantly, in the most recent research, luteolin has been proven to suppress the matrix stiffness-induced biological effects and the CXCR4-mediated yes-associated protein (YAP) signaling pathway in hepatocellular carcinoma (HCC) cells." (PMID 37958980, 2023). "Downregulation of CXCL12/CXCR4 signalling enhanced sensitivity to chemotherapy and impaired tumour growth in a xenograft mouse model of hepatocellular carcinoma." (PMID 36284271, 2022). "Inhibition of CXCR4 significantly enhances sensitivity of hepatoma cells to sorafenib, while high CXCR4 expression correlates with poor response upon sunitinib treatment for metastatic RCC." (PMID 35121728, 2022). "In hepatocellular carcinoma, a CXCR4 antagonist (BPRCX807) combined with sorafenib or anti-PD-1 produced synergistic antitumour effects, extended survival and suppressed distant metastasis." (PMID 35468838, 2022). "CXCR4 expression was also negatively correlated to clinical outcome in patients with hepatocellular carcinoma." (PMID 33635004, 2021). "EFNA1-induced EphA1 activation promotes SDF-1 secretion and endothelial progenitor cell chemotaxis to hepatocellular carcinoma through the SDF-1/CXCR4 signalling pathway." (PMID 34344926, 2021).
hepatocellular carcinoma (continued). "For example, TCF12 expedites hepatocellular carcinoma (HCC) by upregulating CXCR4 and its ligand CXCL12 and activating the MAPK/ERK and PI3K/AKT pathways." (PMID 33413401, 2021). "Previous evidence indicated that suppression of CXCR4 promotes anti-PD-1/PD-L1 efficacy by reshaping the TME in hepatocellular carcinoma." (PMID 34568309, 2021). "Research confirmed that hsa-miR-622 was downregulated in hepatocellular carcinoma, resulting in dysregulation of CXCR4 and KRAS." (PMID 30777071, 2019). "Notably, the presence of CXCR4 has been linked to unfavorable outcomes in multiple different tumor entities, including hematologic malignancies, breast cancer, renal cell carcinoma, gynecologic malignancies, pancreatic adenocarcinoma, and hepatocellular carcinoma." (PMID 31475113, 2019). "CXCR4 is considered a novel marker in tumor endothelium, specifically on tip cells forming the sprouting tumor vessels within hepatocellular carcinoma (HCC)." (PMID 30800123, 2019). "CXCL12/CXCR4 axis blockade in combination with sorafenib treatment was reported to inhibit hepatocellular cancer growth." (PMID 30813533, 2019). "On this regard, recently we reported that CXCL12/CXCR4 axis is involved in migration and invasion of osteosarcoma and hepatocellular carcinoma cell lines through EMT activation." (PMID 29069870, 2017). "Recently, we demonstrated that bone marrow mesenchymal stem cells (BM-MSCs) induce osteosarcoma and hepatocellular carcinoma progression through CXCR4 activation." (PMID 28566721, 2017). "According to our findings, all three hepatoblastoma/hepatoma cell lines only weakly expressed CXCR4 compared to NCI-H69 cells, which, again, fits well with our HCC staining results." (PMID 29282035, 2017). "We found that miR-622 mimic suppressed CXCR4 expression in SK-Hep1 cells, whereas anti-miR-622 increased CXCR4 expression in Huh7 cells, which suggested that miR-622 is a specific regulator of CXCR4 in hepatoma cells." (PMID 26404566, 2015). "To explore the biologic function of CXCR4, we first determined the endogenous CXCR4 expression in hepatoma cell lines, and identified Huh7 and SK-Hep1 cells with the lowest and highest CXCR4 expression for subsequent experiments." (PMID 26404566, 2015). "The CXCR4/CXCL12 has multiple functions at various points in the progression of hepatocellular carcinomas (HCCs)." (PMID 26404566, 2015). "The CXC chemokine receptor 4 (CXCR4) exerts a variety of functions at different steps of hepatocellular carcinoma (HCC) progression." (PMID 26404566, 2015). "Hepatoma cells were transfected with CXCR4 or control siRNA before transfection with anti-miR-622 followed by assessment of cell growth and migration, respectively." (PMID 26404566, 2015). "Suppression of CXCR4 activity either by shRNA or pharmacological inhibition suppresses hepatoma cell growth in vitro and in vivo." (PMID 26404566, 2015). "In this work, we identify CXCR4 overexpression in a subset of HCCs, which contributing to hepatoma cell proliferation, colony formation, migration and survival." (PMID 26404566, 2015). "In this context, the aim of the present study was to investigate the potential effects of FK506 and AMD3100, which is the antagonist of CXCR4, on the Morris rat hepatoma cell line MH3924A." (PMID 24912495, 2014). "Chemokine ligand 12 (CXCL12; stromal cell-derived factor 1) is a homeostatic chemokine that signals through chemokine receptor 4 (CXCR4), which plays an important role in the proliferation of hepatoma cells." (PMID 23737842, 2013). "We thus assessed the role of the SDF-1α/CXCR4 axis in the process of OPN mediated MMP-2 up-regulation in the two human hepatocellular carcinoma cell lines, HepG2 and SMMC7721." (PMID 21909361, 2011). "In this article, through in vitro primary culture methods, we obtained an HCC cell line derived from the human hepatoma portal vein, which provided the experimental materials for a functional study of the role of CXCR4 in tumor cell invasiveness." (PMID 21110890, 2010).